LDHAP3 (lactate dehydrogenase A pseudogene 3)
Synonyms: formerly LDHAL3
Gene: Processed pseudogene on chromosome 2 (41,819,747 to 41,820,754, forward strand). Ensembl gene ENSG00000236090.
Diseases named in the same sentence as LDHAP3 in open-access papers:
LDHAP3 is named in the same sentence as 2 diseases in open-access papers, as found by Europe PMC text mining. Sharing a sentence is not in itself a finding about the gene and the disease. The quoted sentences say what the papers report.
asthma (1 paper, 2021). "The asthma-associated variants in 2p21 near LDHAP3, a locus previously associated with severe asthma exacerbations in Latinos from GALA II, had a predominant effect in males and were nominally significant in the interaction and female-only analyses (p-value < 0.05)." (PMID 34834492, 2021). "Four variants near lactate dehydrogenase A pseudogene 3 (LDHAP3) on 2p21 and 90 variants upstream of the ligand dependent nuclear receptor corepressor-like (LCORL) gene on region 4p15.31 were suggestively associated with asthma, five of them reaching the genome-wide significance." (PMID 34834492, 2021).
LDHAP3 also shares sentences with these, for which no sentence is quoted: melanoma (1 paper).